CXCL1 (C-X-C motif chemokine ligand 1)
Diseases named in the same sentence as CXCL1 in open-access papers (continued):
Sharing a sentence is not in itself a finding about the gene and the disease.
prostate carcinoma (continued). "We further show that obese patients with prostate cancer have increased epithelial CXCL1 expression." (PMID 27241286, 2016). "Using animal models and human tissue samples, the authors show here that ASC recruitment to prostate cancers is mediated by the chemokine CXCL1, which is secreted from tumour cells, and acts on CXCR1 on ASCs." (PMID 27241286, 2016). "These included 8 genes differentially expressed in lethal prostate cancer and highly functionally related to NFκB along with additional promising candidates such as CXCL1, KLF6, and IRF1." (PMID 27078000, 2016). "To use the mouse model for further investigation of CXCL1 function in prostate cancer, we screened a number of mouse tumour cell lines for CXCL1 expression." (PMID 27241286, 2016). "Here we provide evidence that cancer-induced CXCL8 and obesity-dependent CXCL1 gradients regulate ASC trafficking in the context of prostate cancer." (PMID 27241286, 2016). "We show that in prostate cancer CXCL1 expression is obesity dependent, while CXCL8 expression is obesity independent in malignant tumour cells." (PMID 27241286, 2016). "In vitro, knockdown of Ron expression in prostate cancer cells reduced the production of angiogenic chemokines (CXCL1, 5 and 8) leading to a decrease in endothelial cell migration." (PMID 25938541, 2015). "Similarly, in senescent prostate cancer cells induced by Pten gene loss, the SASP, encompassing factors such as IL‐1β, IL‐6, IL‐10, CXCL1 and CSF‐1, attracts MDSCs." (PMID 39270064, 2024). "In line with our observed effects of serum from exercise-trained pancreatic and prostate cancer patients, the growth of BC cells was notably inhibited when supplemented directly with recombinant myokines C-X-C motif ligand 1 (CXCL1), Interleukin 10 (IL10), and C-C motif chemokine ligand 4 (CCL4)." (PMID 39518934, 2024). "Also in chemotherapy, particularly when using oxaliplatin, CXCL1 expression increases in prostate cancer cells which leads to resistance to treatment." (PMID 37108425, 2023). "Therefore, CXCL1 promotes bone metastasis by increasing the number of circulating prostate cancer cells retained in bone." (PMID 37108425, 2023). "Moreover, manipulation of CXCL1 expression using monoclonal antibodies has been shown to influence the rates of proliferation, migration, and invasion of human bladder and prostate cancer cells." (PMID 36614235, 2023). "In contrast, CXCL1 can also inhibit prostate cancer development by reinforcing senescence." (PMID 37108425, 2023). "It is well known that chronic inflamma-tion could lead to the metastasis of prostate cancer cells by regulating the prometastatic and pro-inflammatory feedback loop between CXCL1/-2 and NFκB." (PMID 35855104, 2021). "In the treatment of prostate cancer with oxaliplatin, the expression of CXCL1, CXCL8 and CXCR2 were significantly increased, while CXCR2 inhibitors could enhance the cytotoxicity of oxaliplatin and achieve the combined anti-tumor effect." (PMID 33814009, 2021). "Since two previously defined tumor-associated proinflammatory chemokines (CXCL1 and CCL2) were also detected in addition to the IL1RN, we asked whether there was a correlation in a human prostate cancer clinical dataset." (PMID 33322099, 2020). "Previous studies have shown that urinary protein analysis is a tool for detecting genitourinary diseases including prostate cancer, renal cell carcinoma and BCa, meaning that urinary CXCL1 levels might be affected by other factors in addition to BCa." (PMID 26543745, 2015). "An integrated network of Tgfb2, Il-6, Cxcl1, and Ctgf interactions revealed several putative binding partners in osteoblasts and/or prostate cancer and suggested that these secreted cytokines may control up-regulated transcription factors Junb, Cebpb and Stat3 in osteoblasts." (PMID 27600237, 2015).
prostate carcinoma (continued). "In this study, we identified several genes including the cytokines Il-6, Tgfb2, Cxcl1, and Ctgf, metallopeptidases Mmp13, Adamts1, Adamts4, and Adamts5, and transcription factors Junb, Fos, Stat3 and Cebpb that were up-regulated in osteoblasts as a result of prostate cancer–osteoblast interactions." (PMID 27600237, 2015). "In prostate cancer (PCa), BMAT releases chemokines CXCL1 and CXCL2, which induce osteoclastogenesis through CXCR2 signaling." (PMID 38625510, 2024). "Prostate cancer cells isolated from bone metastasis show the expression of multiple factors including FGF3, FGF19, GDF15, and the described CXCL1." (PMID 37108425, 2023). "CXCL1 belongs to the CXC family chemokine and it has been found to be overexpressed in prostate cancer." (PMID 36836748, 2023). "Nagaya and co-workers identified higher expression of the CXC chemokine signaling genes, including CXCL1, CXCL3, CXCL6, CXCR1 and CXCR2 in prostate cancer bone metastases." (PMID 35328625, 2022). "Mechanistically, TGFβR2-negative prostate CAFs were found to increase CXCL1, CXCL16 and CXCL5 expression and facilitate prostate cancer cell adhesion to bone COL1 fibers to promote skeletal metastasis in C4-2B xenografts." (PMID 36671452, 2022). "Cycling hypoxia increases the expression of both described chemokines (CXCL1 and CXCL2) in PC-3 prostate cancer cells and SK-OV-3 ovarian adenocarcinoma cells." (PMID 33467722, 2021). "As CXCL1 and CXCL2 were predicted as downstream targets of NFκB in prostate cancer, we suggest SELE as another important downstream target in this process." (PMID 27078000, 2016). "Notable genes in the predicted pathway included ATF3, JUNB, KLF6, NR4A2, ZFP36, DUSP5 and NEDD9, as well as STAT3 and IRF1 as novel upstream regulators, and SELE, CXCL1 and CXCL2 as novel downstream targets of NFκB in prostate cancer." (PMID 27078000, 2016). "Our prediction of the chemokine (C-X-C motif) ligand 1 and 2 (CXCL1, CXCL2) as direct and indirect downstream targets of NFκB in prostate cancer can be supported by previous finding in different contexts." (PMID 27078000, 2016). "Our data suggest that ASC recruitment to tumours, driven by CXCL1 and CXCL8, promotes prostate cancer progression." (PMID 27241286, 2016). "CXCL1/GROα decreases the expression of extracellular matrix and plasma protein, fibulin-1D (gene symbol: FBLN1) in prostate cancer cells." (PMID 25814785, 2015). "GRO/GROα (CXCL1), a member of the CXC chemokine family, promotes angiogenesis and recruits neutrophils and endothelial cells during malignant progression in prostate cancer." (PMID 22848758, 2012). "The Top 5 GO molecular functions for the most influential biomarkers in the ABCD‐prostate cancer oncogenic network (IL‐1β, MCP‐1, and CXCL1) are consistently related to glycosaminoglycan/integrin binding and immune receptor activity (predominantly as IL‐1β function)." (PMID 41450167, 2026). "Furthermore, castration-induced CXCL1, CXCL2 and IL-8 from prostate cancer cells mediate myeloid infiltration, particularly of MDSCs, resulting in an immunosuppressive TME17,18." (PMID 39633050, 2025). "Studies on mouse cells have shown that marrow adipocytes under the influence of factors from prostate cancer secrete CXCR2 ligands, which indicates that CXCL1 may work via this mechanism, although this needs to be confirmed on human cells." (PMID 37108425, 2023). "In addition, HDAC1-shRNA decreased the effect of CXCL1/GROα on migration and invasion, suggesting that HDAC1 is also involved in CXCL1/GROα-mediated prostate cancer progression." (PMID 28624794, 2017). "Curcumin reduced the levels of chemotactic cytokines CXCL-1 and -2, cyclooxygenase (COX), secreted protein acidic and cysteine-rich (SPARC)/osteonectin and EGF-containing fibulin-like extracellular matrix protein 1 (EFEMP) proteins in PC-3 prostate cancer cells." (PMID 30823649, 2019).
prostate carcinoma (continued). "CXCL1 (chemokine with C-X-C motif ligand 1) is a member of the CXC chemokine family and promotes neoplastic transformation, tumorigenesis, and angiogenesis in breast, lung, pancreatic, colorectal, bladder, and prostate cancer, as well as in melanoma, by binding specifically to CXCR2." (PMID 27542259, 2016).
gastric cancer (60 papers, 2012 to 2026). A primary or metastatic malignant neoplasm involving the stomach. "This inflammatory signature mirrors the tumor microenvironment of human KRAS-mutated gastric cancers, which often exhibit elevated interleukin-6 signaling and enhanced C-X-C motif chemokine ligand 1-mediated neutrophil recruitment." (PMID 40673273, 2025). "The elevated expression of CXCL1 in gastric cancer tumors is associated with an increase in the expression of this chemokine in an autocrine manner in gastric cancer cells." (PMID 37408240, 2023). "CXCL1 is closely associated with tumorigenesis in gastric cancer, as CXCL1 expression is positively correlated with advanced TNM stage, i.e., T invasion stage, lymph node metastasis, as well as tumor size." (PMID 37408240, 2023). "Higher levels of CXCL1 in gastric cancer have been associated with tumor progression and reduced patient survival." (PMID 34183723, 2021). "Both in ovarian and gastric cancer patients, CXCL1 expression is associated with poorer prognosis compared to CXCL1-negativity." (PMID 34503058, 2021). "CXCL1 upregulation was one of the independent prognostic factors for gastric cancer patient’s survival and was significantly associated with tumor progression of gastric cancer patients." (PMID 31803057, 2019). "CXCL1 expression in gastric cancer was shown to be associated with vascular endothelial growth factor (VEGF) and p-STAT3 expression, advanced tumor stage and poor prognosis." (PMID 28575019, 2017). "Using immunohistochemistry, they also showed that the expression level of CXCL1 in human gastric cancer tissues was associated with lymph node metastasis and TNM classification." (PMID 29285315, 2017). "Previously, our group showed a significant association of CXCR2 and CXCL1 over-expression (n = 116) with gastric cancer progression." (PMID 22479608, 2012). "High expression of migration-related factors, such as cyclooxygenase 2 (COX-2), Vascular endothelial growth factor (VEGF), CXC chemokine ligand (CXCL)-8, chemokine (C-X-C motif) receptor (CXCR)-2, and CXCL-1, are associated with gastric cancer progression." (PMID 22479608, 2012). "Similarly, CXCL1 secreted by tumor associated lymphatic endothelial cells (TLECs) contributes to gastric cancer adhesion, invasion and metastasis by activating integrin β1-FAK-AKT signaling pathway." (PMID 40248695, 2025). "Overexpression of CXCL1 in gastric cancer is associated with increased migration and invasion of gastric cancer cells, indicating that CXCL1 and its receptors could be potential targets for gastric cancer therapy." (PMID 38791448, 2024). "That indicates that CXCL1 in gastric cancer causes lymphangiogenesis." (PMID 37408240, 2023). "Also, CXCL1 secreted by gastric cancer cells was reported as a key diagnostic and prognostic biomarker for the pathogenic progression of gastric cancer." (PMID 36614235, 2023). "Higher CXCL1 expression in gastric cancer tumors is associated with worse overall survival, although there is also one study where high CXCL1 expression was associated with a better prognosis for gastric cancer patients." (PMID 37408240, 2023). "Gastric cancer cells can increase CXCL1 expression in tumor-associated cells." (PMID 37408240, 2023). "Previously, we reported that elevated CXCL1 and CXCR2 in gastric cancer is associated with tumor progression, and that the plasma CXCL1 level may be a useful circulating biomarker for gastric cancer diagnosis." (PMID 22479608, 2012). "In GC models, lactate-induced H3K18 lactylation upregulates VCAM1 transcription, activates AKT-mTOR signaling, enhances CXCL1 secretion, and expands GC-derived mesenchymal stem cells and M2 macrophages, collectively accelerating gastric cancer progression." (PMID 40703527, 2025).
gastric cancer (continued). "CXCL1, in turn, promote LECs’ migration and tube formation, thereby facilitating gastric cancer metastasis." (PMID 40248695, 2025). "The upregulation of IL-1α/β and CXCL1/5 reflects the inflammatory cascade observed in human gastric cancer, where these cytokines promote neutrophil infiltration, angiogenesis, and epithelial-mesenchymal transition." (PMID 40673273, 2025). "PPI network analysis highlighted eight key hub genes (CD80, CCR9, CXCR3, CXCR5, CXCR6, CCR3, CCL20, and CXCL1), revealing their pivotal roles in gastric cancer and H. pylori infection." (PMID 40445003, 2025). "A co-culture experiment with gastric cancer cells and lymphatic endothelial cells (LECs) demonstrated that cancer cells can stimulate LECs to secret CXCL1 via NF-κB pathway." (PMID 40248695, 2025). "While biomarkers like CXCL1 and CCL20 are linked to H. pylori–driven inflammation, their elevation in H. pylori gastric cancer samples indicates broader relevance to gastric cancer pathology." (PMID 40445003, 2025). "LEC migration and tube formation involving FAK-ERK1/2-RhoA activation and F-actin recombination were subsequently triggered by CXCL1, which in turn led to the end result of metastasis of gastric cancer tumors." (PMID 39090094, 2024). "CXCL1 in gastric cancer tumors also comes from fibroblasts which increase CXCL1 expression under the influence of extracellular vesicles from gastric cancer cells." (PMID 37408240, 2023). "Consistently, our results showed a higher CXCL1 expression in gastric cancer patient samples, which was positively correlated with CXCR2 expression." (PMID 36614235, 2023). "For this reason, CXCL1 levels in gastric cancer tumors are positively correlated with lymphatic metastasis." (PMID 37408240, 2023). "CXCL1 induces an increase in the expression of MMP2 and MMP9 in gastric cancer and causes the migration of LEC, especially to lymphatic vessels, which results in lymphatic metastasis." (PMID 37408240, 2023). "In gastric cancer as well, CXCL1-overexpressing tumor cells showed increased migratory and invasive potential, whereas CXCL1 depletion significantly decreased the carcinogenic activities." (PMID 36614235, 2023). "CXCL1 increases gastric cancer cell proliferation, as shown by experiments on HGC27 cells, AGS, Hs746T." (PMID 37408240, 2023). "Gastric cancer cells secrete factors that increase CXCL1 expression in LEC as a result of NF-κB activation in LEC." (PMID 37408240, 2023). "Our results showed that CXCL1 is highly expressed in both gastric cancer tissues and gastric cancer cells infected with H. pylori." (PMID 36614235, 2023). "Here in this study, the gastric cancer microenvironment analysis revealed increased tumor tissue infiltration of monocytes and macrophages which strongly and positively correlated with CXCL1 expression." (PMID 36614235, 2023). "Gastric cancer tumors show a higher expression of CXCL1 and CXCL8 than healthy gastric tissue; the expression of both of these chemokines is highest in diffuse-type gastric carcinoma." (PMID 37408240, 2023). "The positive correlation of CXCL1 expression with worse overall survival of gastric cancer patients is related to the fact that CXCL1 participates in tumorigenic processes." (PMID 37408240, 2023). "To study the role of CXCL1 in tumorigenesis, we investigated the infiltrating immune cells in the gastric cancer tumor microenvironment (TME)." (PMID 36614235, 2023). "In silico analysis showed that CXCL1 is highly expressed in gastric cancer tissues and gastric cancer cells infected with H. pylori." (PMID 36614235, 2023). "We have shown that CXCL1 expression is higher and promoter methylation levels are lower in gastric cancer patients and H. pylori-infected gastric cells compared to healthy subjects and control cells." (PMID 36614235, 2023). "Protein–protein interaction and co-expression analysis showed a strong association of CXCL1 with CXCR1, CXCR2, IL6, and IL1B in human gastric cancer tissue samples." (PMID 36614235, 2023).